STAT3 (signal transducer and activator of transcription 3)
Diseases named in the same sentence as STAT3 in open-access papers (continued):
Sharing a sentence is not in itself a finding about the gene and the disease.
gastric cancer (continued). "Thus, upregulation of SHP-1 might be an important issue for effective dephosphorylation and inhibition of STAT3 in gastric cancer cells." (PMID 29409467, 2018). "Thus, SHP-1 may be a promising phosphatase for inactivation of STAT3 signaling in gastric cancer cells, and the biologic function of SHP-1 in gastric cancer needs to be further evaluated in future studies." (PMID 29409467, 2018). "In support of this, immunohistochemical analysis of gastric adenocarcinoma tissues showed that STAT3 expression is closely associated with tumour, node and metastasis (TNM) stage as well as survival, suggesting that it functions as a biomarker predicting poor prognosis of gastric cancer." (PMID 29383166, 2017). "Thus, NF-κB and STAT3 contribute to gastric cancer development and progression." (PMID 28350359, 2017). "In gastric cancer cell lines, CD44v6 involved in cell proliferation, invasion and metastasis in Next, report on a novel mechanism by which interleukin-6/signal transducer and activator of transcription 3 (IL-6/STAT3) signaling up-regulates expression of CD44v6." (PMID 28507278, 2017). "Similarly, treatment of quiescent gastric cancer stem cells with IL‐17 also results in EMT‐like changes including E‐cadherin loss, de novo vimentin acquisition, and increased migratory and invasive properties and associates with STAT3 phosphorylation." (PMID 28599100, 2017). "Taken together, these results suggest that CAFs in the tumor microenvironment promote the progression of gastric cancer through IL-6/JAK2/STAT3 signaling, and IL-6 targeted therapy could be a complementary approach against gastric cancer by exerting their action on stromal fibroblasts." (PMID 28186964, 2017). "Here, another possible feedback mechanism and clinical significance of EZH2 and STAT3 were investigated in gastric cancer (GC)." (PMID 27938379, 2016). "Moreover, activation of TGR5 significantly inhibits STAT3 phosphorylation and transcriptional activity in gastric cancer cells, which suggests that TGR5 is a potential tumor suppressor via suppression of the STAT3 pathway, a commonly constitutively active pathway in cancer cells." (PMID 27781093, 2016). "Given the important role of STAT3 and Akt activation in cell growth, proliferation and survival in many human cancers, including gastric cancer, further studies were designed to explore the effects of miR-148a on activation of STAT3 and Akt in gastric cancer cells." (PMID 27518872, 2016). "By comparing the blood donors with the patients with gastric cancer, a significant difference was observed in the frequency of CagA positive status (p < 0.001; OR = 8.54; 95 % CI = 4.99 – 14.76) and in the distribution of the STAT3 genotypes (χ2 = 10.86, 2 degrees of freedom, p = 0.004)." (PMID 26186918, 2015). "Hence, in agreement with the present microarray data, treatment with GO-Y031 significantly decreased the numbers of pSTAT3-activated cells in mice with gastric cancer, indicating that this curcumin analog may inhibit the phosphorylation of STAT3." (PMID 25331984, 2015). "Moreover, IL-6 activated STAT3 in gastric cancer cells in a dose-dependent fashion." (PMID 25785838, 2015). "IL-1α and IL-1β mRNA expression is upregulated in antral tumors of gp130757FF mice, consistent with the view that IL-1RT1 ligands may contribute to the development of gastric antral tumors in this STAT3-dependent model, and may serve as novel therapeutic targets for gastric cancer." (PMID 25528766, 2015).
gastric cancer (continued). "Taking these considerations together and the fact that to date there are no studies evaluating the STAT3 polymorphism and risk of gastric cancer in Western populations; we assessed the STAT3 polymorphism and CagA status as well as EPIYA-C pattern of H. pylori strains and risk of gastric cancer." (PMID 26186918, 2015). "Therefore, it is necessary to confirm that (i) the role of H. pylori-mediated upregulation of IL-22 in gastric cancer cells, (ii) the activation of STAT3 dependent on H. pylori-mediated IL-22 and/or H. pylori CagA, (iii) the role of CagA in H. pylori-mediated upregulation of IL-22." (PMID 26160167, 2015). "Our data support the hypothesis that cancer cells may undergo adaptive changes after anti-tumor therapies (either chemotherapy or targeted therapy) and also demonstrate that the IL-6/STAT3/Jagged-1/Notch signaling pathway exerts critical functions in trastuzumab resistant gastric cancer cells." (PMID 25669984, 2015). "Thus, inhibition of STAT3 transcriptional activity in human gastric cancer may provide a possible means of reducing the high morbidity and prolong life amongst gastric cancer patients worldwide." (PMID 24804649, 2014). "Therefore, inhibition of the IL-6/STAT3 signaling pathway may provide a new therapeutic strategy against gastric cancer." (PMID 24116074, 2013). "Moreover, IL-6 and STAT3 downstream signals such as IL-10 and VEGF were reduced in patients after removal of gastric cancer as compared to pre-operation, this was associated with recovery of T lymphocytes and NK cells in peripheral circulation in these patients." (PMID 24116074, 2013). "Thus, our result suggests that dual inhibition of PI3K and STAT3 signaling may be an effective therapeutic strategy for KRAS mutant gastric cancer patients." (PMID 22159814, 2012). "In HER2-positive breast and gastric cancers, ERBB2-driven STAT3 activation is a key mechanism contributing to tumor aggressiveness and resistance to targeted therapy." (PMID 41516350, 2026). "Collectively, our findings reveal a previously unrecognized role of PISD in linking mitochondrial phospholipid metabolism to STAT3/GPX4-dependent ferroptosis, providing mechanistic insights into the regulation of ferroptosis in gastric cancer." (PMID 41899452, 2026). "For example, lncRNA PVT1 promotes angiogenesis by stabilizing STAT3, which then activates the STAT3/VEGFA signaling axis that drives upregulation of VEGF expression and tumor progression in gastric cancer—this is likely relevant to other cancers as well." (PMID 41154428, 2025). "A study reported that the expression of CXCR4 and CXCR2 is positively correlated in gastric cancer and that a positive feedback loop is formed between P65/CXCR4 and STAT3/CXCR2, which induces EMT and promotes metastasis." (PMID 40722739, 2025). "TANs produce IL-17a, which promotes EMT of GC cells through JAK2/STAT3 signaling in gastric cancer." (PMID 40564191, 2025). "Overexpression of RBMS1 in HGC-27 and SGC-7901 cells increased the migration and invasion of gastric cancer cells by binding to the transcription factor MYC and activating the IL-6/JAK2/STAT3 signaling pathway." (PMID 41214391, 2025). "TANs secrete IL-17A via the JAK2/STAT3 signaling pathway, which promotes EMT in gastric cancer cells." (PMID 40387965, 2025). "In the context of gastric cancer, it promotes apoptosis through reactive oxygen species (ROS)-dependent signaling pathways, such as MAPK, STAT3, and NF-κB." (PMID 40141751, 2025). "To explore whether heterozygous Rnpc3 reduces tumour burden more broadly, we employed a mouse model of gastric cancer in which adenomas develop due to a tyrosine (Y) to phenylalanine (F) mutation at codon 757 of the cytokine receptor GP130, leading to persistent activation of STAT3." (PMID 40624356, 2025).
gastric cancer (continued). "For example, they demonstrated that CAFs enhance the migration and EMT of gastric cancer cells by activating the Janus kinase 2/signal transducer and activator of transcription (JAK2/STAT3) pathway in gastric cancer cells by secreting IL-6." (PMID 40485724, 2025). "Strains expressing CagA strongly activate extracellular signal-regulated kinase 1/2 (ERK1/2), STAT3, and increase IL-6 and −11 levels, which results in the aggravating of HAG and gastric cancer." (PMID 40264171, 2025). "In gastric cancer, AKR1B1 plays a pro-tumorigenic role through modulation of ferroptosis via interaction with STAT3 and p-STAT3." (PMID 41154825, 2025). "In gastric cancer, macrophage-derived CXCL5 promotes tumor cell migration through the CXCR2/STAT3 pathway and facilitates chemoresistance via the CXCL5/PI3K/AKT/mTOR pathway." (PMID 38642131, 2024). "It is overexpressed in gastric cancer cells and influences the proliferation, migration, invasion and adhesion of gastric cancer cells by regulating the JAK2/STAT3 signaling pathway accelerating the progression of gastric cancer." (PMID 37505298, 2024). "In gastric cancer, IL6 can exert its influence on invasion and progression via the activation of the JAK2/STAT3 pathway, which is the well-known signaling pathway induced by IL6." (PMID 39251966, 2024). "In gastric cancer, the overexpression of SCIN is associated with poor overall survival rate, and it changes significantly in stages I and IV, stage II and IV, and stage III and IV, which may promote the progression of gastric cancer by regulating STAT3 and NF-κB signaling." (PMID 39108273, 2024). "NF-κB activation and hypermethylation-mediated silencing of miR490-3p by H. pylori lead to DARPP-32 overexpression in gastric cancer cells thereby activating PI3K/AKT and STAT3 signaling pathways." (PMID 38233872, 2024). "However, the combined use of STAT3 inhibitors with PI3K/AKT/mTOR inhibitors can synergistically induce apoptosis in PTEN-deficient cancer cell lines, highlighting the potential of this combined therapeutic strategy in the treatment of PTEN-deficient tumors, including gastric cancer." (PMID 39309860, 2024). "By modulating the activity of HIF-1α and c-Myc, STAT3 significantly enhances AEG and proliferation in gastric cancer cells, underscoring its pivotal role in the SIRT6-regulated AEG pathway." (PMID 39906672, 2024). "In gastric cancer, CPX has been reported to reduce signal transducer and activator of transcription 3 (STAT3) phosphorylation, leading to cell growth arrest and autophagic death." (PMID 39487118, 2024). "TANs secrete IL-17a, enhancing the migration, invasion, and EMT of gastric cancer cells, while activating the JAK2/STAT3 signaling pathway in these cells." (PMID 39676857, 2024). "One study shows that JAK2 or STAT3 inhibitor reduces 5-FU resistance and autophagy through ATF6-mediated ER stress in gastric cancer cells, which also enhances the sensitivity of gastric cancer cells for 5-FU." (PMID 38536006, 2024). "The triad of “IL-6+p-Stat3+PD-1+ cell differentiation” is a key indicator of survival and is more reliable than the traditional TNM classification in determining postsurgical gastric cancer prognosis." (PMID 39309860, 2024). "Activating JAK2/STAT3 signaling pathway promotes EMT, migration, and invasion of gastric cancer cells, and promotes the transformation of quiescent gastric CSCs into invasive gastric CSCs." (PMID 39906741, 2024). "Surprisingly, expression of YAP1, STAT3, IL11, or IL6 mRNA transcripts remained comparable across the molecular subtypes of gastric cancer." (PMID 37957015, 2024). "We used this dataset to evaluate the expression patterns of YAP1, STAT3, IL11, IL6, TEAD1, IL6ST, and IL11RA in gastric cancer patients within the four TME subtypes." (PMID 37957015, 2024). "An optimized compound 2 exhibited in vitro and in vivo anti-gastric cancer activity partly through inhibiting the AKT and STAT3 pathways, and displayed a favorable in vivo safety profile." (PMID 38385332, 2024).
gastric cancer (continued). "Silencing this lncRNA increased the levels of DC-SIGN in gastric cancer cells and increased the activity of the JAK2/STAT3 signaling cascade." (PMID 39309860, 2024). "Several signaling pathways, including Notch in gastric cancer, JNK/STAT3 in hepatocytes, and EGFR in oral cancer, regulate autophagy and support CSC survival." (PMID 39456967, 2024). "Iron ions induce iron-induced cell death and can alter the drug resistance of gastric cancer cells through pathways such as KEAP1/NRF2, STAT3, and Nrf2/Keap1/xCT." (PMID 38370477, 2024). "Inhibiting the STAT3/MSK1/NFATc2 axis, including calcium blockers, can substantially decrease the proliferation and growth of gastric cancer cells in xenograft models." (PMID 39309860, 2024). "In gastric cancer cells, single stranded interacting protein 1 (RBMS1) was discovered to activate the JAK2/STAT3 downstream signaling pathway after binding to the transcription factor MYC, subsequently increasing cancer migration and invasion." (PMID 38182570, 2024). "Within this context, RNA-sequencing analysis in gastric cancer uncovered a link between macrophage-derived IL-10 and the activation of c-MET/STAT3 signaling pathways." (PMID 39664377, 2024). "Similar functional findings were also consistently noted when ADAR1 was overexpressed in NUGC3 gastric cancer cell, when ADAR1 was repressed in MKN28 gastric cancer cell, or when STAT3 was repressed in GC 5FU + CDDP resistant organoid." (PMID 37208334, 2023). "In vitro studies silencing STAT3 by specific siRNA reduced proliferation and increased the percentage of apoptosis of human SGC-7901 gastric cancer cells." (PMID 38067351, 2023). "We next focused on the relationship between STAT3 and PIAS, as well as the five-year survival rate of patients with gastric cancer." (PMID 36672337, 2023). "Studies have shown that asiatic acid derivatives can inhibit gastric cancer cell proliferation and invasion by suppressing JAK2 and STAT3 activation." (PMID 37375849, 2023). "Signal Transducer and Activator of Transcription 3 (STAT3) has emerged through an extensive array of investigations, as a tantalizing therapeutic target for gastric cancer, offering hope in this challenging landscape." (PMID 38023173, 2023). "In vitro models of gastric cancer and xenografted tumors have also shown that MIA-602 can downregulate the PAK-1-mediated STAT3/NF-κB inflammatory pathway." (PMID 37370714, 2023). "Like PARP inhibitors, STAT3 inhibitors down-regulate SLC7A11 and GPX4 to trigger ferroptosis, inhibit gastric cancer progression and reduce chemoresistance." (PMID 37313458, 2023). "Helicobacter pylori infection increases the expression of FGFR4 in gastric cancer cells through activation of the STAT3 pathway by FGF19, and STAT3 binds directly to the FGFR4 promoter, forming a feed‐forward response loop." (PMID 37750089, 2023). "On the other hand, SFN-treated gastric cancer cells exhibited higher activation of miR-124, which directly targets the 3′-untranslated regions (UTR) of IL-6R and STAT3, thus preventing stemness characteristics." (PMID 36776295, 2023). "CircUBE2Q2 acts as a sponge for miR-370-3p, activating the STAT3 pathway to promote PFK and HK2 expression, thereby increasing glycolysis levels in gastric cancer cells and promoting cell proliferation and migration." (PMID 37599427, 2023). "IL-6 activated the STAT3 signaling pathway and induced cancer stemness by upregulating the expression of OCT4 and CD44 in gastric cancer cells." (PMID 36838713, 2023). "In gastric cancer, LY96 can activate macrophage-mediated NF-κB and STAT3 pathways to promote tumor progression." (PMID 37662929, 2023). "We demonstrated that PA treatment for 12 h decreased the expressions of p-STAT3, p-JAK2, N-cadherin, and vimentin, and inhibited the nuclear expression of p-STAT3 in gastric cancer cells." (PMID 36672337, 2023). "In gastric cancer, piperine repressed IL-1β expression, resulting in inhibition of p38/MAPK and STAT3 activation." (PMID 36678600, 2023).
gastric cancer (continued). "In the current study, we are the first to identify miR-877-3p with upregulation in the chemo survived gastric cancer cells, which was mediated by GM-CSF induction but in turn suppressed SOCS2 and activated Jak/Stat3 signaling." (PMID 35600882, 2022). "Our data provide a glimpse of CAMKK2-regulated tyrosine signaling in gastric cancer cells, which involves the PTK2/JUN/STAT3 axis." (PMID 35646067, 2022). "Furthermore, gastric cancer (GC)-MSCs-derived IL-15 is reported to promote EMT of GC cells via STAT3 activation." (PMID 35842634, 2022). "EIF3B promoted gastric cancer cell proliferation, enhanced tumor cell migration and invasion through epithelial-mesenchymal transition (EMT) and the Stat3 signaling pathway in numerous human cancers." (PMID 35008908, 2022). "For example, extracellular vesicles derived from gastric cancer cells can increase the expression of PDL1 in neutrophils, which is achieved by activating signal transducer and activator of transcription 3 (STAT3)." (PMID 35676257, 2022). "Another study demonstrated that TQ treatment inhibited the phosphorylation of STAT3 in HGC27, SGC7901, and BGC823 gastric cancer cells, and inhibited the phosphorylation of JAK2 in HGC27 cells." (PMID 36145344, 2022). "In gastric cancer cells, PVT1 interacts with STAT3 and protects STAT3 from poly-ubiquitination and proteasome-dependent degradation to sustain the stability of p-STA3." (PMID 36295083, 2022). "PML/RARα is known to enhance STAT3 expression, and STAT3 has been reported to epigenetically silence NR4A3 expression in gastric cancer." (PMID 36040481, 2022). "It has been reported that HOXA10 deteriorates gastric cancer through inducing Bcl-2 expression and activating JAK1/STAT3 signaling pathway." (PMID 36407869, 2022). "Our data show a decrease in the phosphorylation of TYK2 at Y292 and STAT3 at Y705 and Y737 on inhibition of CAMKK2 in gastric cancer." (PMID 35646067, 2022). "We have reported decreased phosphorylation of TYK2 at Y292, PTK2 at Y662, and STAT3 at Y705, Y737 upon inhibition of CAMKK2 in gastric cancer cells." (PMID 35646067, 2022). "Compared to normal fibroblasts CAFs overexpress TGFβ and other proteins and secrete IL-22 into the tumor microenvironment which promotes cell invasion via STAT3 and ERK pathways in gastric cancer." (PMID 34854061, 2022). "For example, miR-106a-3p induced apatinib resistance in gastric cancer cells by targeting the Cytokine signaling (SOCS) system and activating Jak2/Stat3 signaling." (PMID 35600882, 2022). "In conclusion, our results illustrated that palmitic acid/p-STAT3/miR-193a-3p/LAMC1 pathway promotes preadipocyte differentiation, pre-metastatic niche formation and gastric cancer cell colonization to peritoneum." (PMID 35541892, 2022). "Remarkably, STAT3 depletion, lncRNA RPSAP52 depletion and miR-665 overexpression functions equally in gastric cancer." (PMID 35322746, 2022). "In gastric cancer, RNF6 regulates cancer cell growth by affecting the SHP-1/STAT3 signaling pathway." (PMID 35369571, 2022). "In hypoxic conditions, the STAT3-G9a complex inhibits autophagy in gastric cancer (GC)." (PMID 35740522, 2022). "It is shown that Signal Transducer and Activator of Transcription 3 (STAT3) and caudal type homeobox 1 (CDX1) promote SALL4 expression in breast and gastric cancers, respectively." (PMID 36010677, 2022). "Luteolin, another component of MO, which has been found to reduce gastric cancer cells growth and cancer metastasis in vitro and in vivo via regulating Notch1, PI3K, AKT, mTOR, ERK, STAT3, and P38 signaling pathways." (PMID 35889404, 2022). "Glycitein had significant cytotoxic effects on gastric cancer cells by inducing cell apoptosis and G0/G1 phase cell cycle arrest via the ROS-related MAPK/STAT3/NF-κB signaling pathway." (PMID 36437827, 2022).